MIR499B (microRNA 499b)
Synonyms: hsa-mir-499a; MIR499A; hsa-mir-499b
Gene: MicroRNA gene on chromosome 20 (34,990,400 to 34,990,472, reverse strand). Ensembl gene ENSG00000283441.
Gene Ontology:
Biological process: miRNA-mediated post-transcriptional gene silencing
Cellular component: RISC complex